CD4 (CD4 molecule)
Diseases named in the same sentence as CD4 in open-access papers (continued):
Sharing a sentence is not in itself a finding about the gene and the disease.
Sepsis (continued). "This clinical study was designed to evaluate the intensity of ERS and its associated CD4+ T cell apoptosis in elderly sepsis patients, and explore the correlation between mTOR-mediated autophagic-lysosomal disorder and ERS, providing evidence for future preclinical and clinical research." (PMID 40933998, 2025). "The phenotype and effector functions of CD4+ T cells have also been linked to sepsis." (PMID 40909263, 2025). "Indeed, dendritic cells loss and dysfunction, CD4+ T cells apoptosis and exhaustion, and B cell apoptosis have been described following sepsis." (PMID 40784979, 2025). "Uncontrolled HIV infection with low CD4+ T cell counts has been associated with more severe disease manifestations, including extensive and necrotizing skin lesions, pulmonary involvement, secondary infections, prolonged illness, sepsis, and higher mortality." (PMID 41476947, 2025). "Further elucidation of the causes of CD4+ T cell exhaustion in high-risk C1 sepsis patients is necessary, as it may be closely associated with disturbances in the immune microenvironment." (PMID 41306770, 2025). "Moreover, we demonstrate that a higher frequency of circulating CD4+ and CD8+ lymphocytes express either the ligand (AREG) or receptor (EGFR) ex vivo, in sepsis, and expression of CD4+ lymphocyte EGFR was associated with several features of immunosuppression." (PMID 41063987, 2025). "Fifthly, while we corroborated the critical role of ZBP1 in NUFIP1-mediated ribophagy associated with CD4+ T lymphocytes’ PANoptosis in sepsis, the precise interactional dynamics and underlying molecular mechanisms between these proteins remain to be elucidated." (PMID 40995563, 2025). "Significant expression of the ribophagy-specific receptor NUFIP1 and autophagy-associated protein LC-3B was observed in CD4+ T lymphocytes after sepsis, with a corresponding decrease in the expression of ribosomal self-proteins ribosomal protein L7 (RPL7), RPL23, and RPL26." (PMID 40995563, 2025). "The aim of this study was to clarify the relationship between expression level of CTLA-4 on CD4+ T cells and sepsis-associated immunosuppression (SAI), and to elucidate the possible mechanism of mTOR pathway mediated autophagic-lysosomal disorder in regulating CTLA-4 expression." (PMID 39104530, 2024). "Additionally, we found that the activation and differentiation of CD4+‐naive T cells are also linked to low expression of LGALS9 in sepsis patients." (PMID 39044269, 2024). "Furthermore, metabolic reprogramming and dysregulated IL-17 production persist after sepsis resolution, impairing CD4+ T cell function and increasing the risk of infection-related readmission and mortality in sepsis survivors." (PMID 39712019, 2024). "The inverse variance-weighted analysis disclosed that the absolute count of CD4 regulatory T cells (CD4 Treg AC) within the lymphocyte subgroup has a causative link to an elevated risk of sepsis, with an odds ratio of 1.08 and a 95% confidence interval of 1.02 to 1.15 (P = .011)." (PMID 39465765, 2024). "Moreover, diminished levels of adaptive immune cells like CD8+ and CD4+ T cells, as well as B cells, have been linked to the progression of sepsis." (PMID 39671358, 2024). "In summary, we may have found a contribution of the mTOR-autophagy-CTLA4 axis in sepsis-associated CD4+ T cell deficiency and dysfunction." (PMID 39104632, 2024). "Sepsis is associated with apoptosis of Tem cells in both the periphery and lymphoid organs, inducing immunoparalysis, and anti–miR-93-5p therapy appeared to block this phenomenon in the periphery and especially for the CD4+ Tem subtype of lymphocytes." (PMID 37261908, 2023). "Numbers of CD4 T cells decrease after the onset of sepsis, and absolute CD4 T-cell numbers return to pre-septic levels after a month in most patients, but failure to restore sufficient numbers of immunocompetent CD4 T cells is associated with a poor prognosis." (PMID 38114466, 2023).
Sepsis (continued). "Therefore, we designed the present study to investigate the molecular mechanisms underlying autophagic flux deficiency in CD4 + T cells during sepsis and to explore the roles of mTOR pathway in modulating CD4 + T cell survival." (PMID 35435531, 2022). "We speculate that mTOR might also function as import regulator during the process of CD4+ T cell apoptosis caused by ERS in sepsis." (PMID 35915740, 2022). "Therefore, we designed the present study to investigate the mechanisms underlying excessive apoptosis of CD4 + T cells during sepsis." (PMID 35435531, 2022). "Stimulated splenocytes from septic JAM-A–/– mice had decreased frequency of TNF+CD4+ cells and elevated frequency of IL-2+CD4+ cells, both of which could alter antimicrobial response and potentially play a causative role in improved survival from sepsis." (PMID 35819838, 2022). "CD4+ PD-1+ expression levels and high heart rate are potential risk factors for sepsis." (PMID 36010357, 2022). "The absolute number of CD4+TIM-3+, CD4+PD-1+, and CD4+CTLA-4+ T cells were positively correlated with the severity of sepsis, especially CD4+PD-1+ T cells, which may be a risk factor for sepsis." (PMID 35281010, 2022). "In summary, this is the first study to compare the efficacies of clinically relevant doses, administration routes, and timing of cholecalciferol and calcitriol treatments on MLN CD4+ T cell polarization and associated intestinal injury in obesity concurrent with sepsis." (PMID 36079813, 2022). "Additionally, the ratio of CD3+CD4+CD69+T/CD3+CD8+CD69+T ≤ 0.2697 was an independent risk factor for poor ICU discharge in G- sepsis patients (HR: 0.34 (0.13, 0.88), P=0.026)." (PMID 36703970, 2022). "An in-depth analysis of the differences in immune cell abundance between the high- and low-risk groups for sepsis showed that CD4 memory activated T cells, Tregs, resting NK cells, M0 macrophages, and M2 macrophages were higher in the high-risk group than in the low-risk group." (PMID 36389695, 2022). "Sepsis induced apoptosis causes profound depletion of B and CD4+ T lymphocytes in humans." (PMID 32677895, 2020). "In addition, we also revealed that elevations in M0 macrophages, M2 macrophages, naïve B cells, and naïve CD4 T cells in peripheral blood were independent risk factors for poor prognosis in sepsis at onset." (PMID 33344482, 2020). "The cohoused mice showed a significant reduction in number of Ag-experienced (CD11+CD4d+) and naïve (CD11a−CD49d−) CD4 T cells in the spleen 2 days after CLP that returned to sham levels by day 30, indicating entire CD4 T cell compartment is susceptible to sepsis-induced numerical reduction." (PMID 32903436, 2020). "CD4+ T cells are important for regulation and orchestration of immune response and their impairment leads to loss of functional immune cells and subsequent immunosuppression; characteristic feature very often induced during sepsis." (PMID 32949213, 2020). "Thus, sepsis causes global changes in expression of factors regulating CD4 T cell effector responses, which limits help provided to other immune cells and effectiveness of de novo immune responses." (PMID 32733454, 2020). "Another possibility concerns the differences between systemic and mucosal DCs in inducing CD4 T-cell responses during sepsis, which could be caused by the transition of the intestinal microbiome to a “pathobiome”." (PMID 31323786, 2019). "CD4+ depleted mice were still protected against septicaemia, whereas no protection was seen in antibody deficient mice, and passive transfer of serum from colonized mice into immune naïve mice also protected against S. pneumoniae septicaemia." (PMID 30881363, 2019). "Herein, we investigated whether Mdivi-1 affects apoptosis of CD4+ T cells in sepsis and the potential underlying mechanisms." (PMID 31263382, 2019). "Sepsis is associated with decrease in the frequencies and numbers of CD4 T cells." (PMID 30052667, 2018).
Sepsis (continued). "Thus, prevention of the loss of CD4 T cells is an effective therapeutic approach to improve the immune function and reduce the mortality in sepsis." (PMID 30052667, 2018). "Sepsis is associated with immunoparalysis, as apoptosis of CD4+ and CD8+ T cells is increased." (PMID 29954328, 2018). "Decrease of CD4 T cell numbers causes immunosuppression in sepsis." (PMID 30052667, 2018). "In sum, the immunophenotypic landscape of cancer septic animals is characterized by both increased CD4+ T cell activation and exhaustion, findings that may underlie the observed increased mortality in mice with pre-existing malignancy following sepsis." (PMID 29338031, 2018). "Therefore, both apoptosis and impaired proliferation of CD4 T cells are the key events to cause their reduction in numbers in sepsis." (PMID 30052667, 2018). "We also found that the increased rate of CD4 T cell proliferation in sepsis following treatment with ghrelin was directly linked with the increased expression of cell cycle positive regulators cyclin D1 and cyclin B1 and decreased expression of the cell cycle negative regulator p57." (PMID 30052667, 2018). "These clinical data indicate that IL‐10 may contribute to the increased percentage of Treg cells among the CD4+ T‐cell population under septic conditions, thus contributing to the immunosuppressive state associated with refractory sepsis." (PMID 30238076, 2018). "Furthermore, the preceding study also showed that BTLA deficient mice (BTLA−/−) had increased numbers of CD4+ T cells in the spleen following sepsis and implicated a role for BTLA in apoptosis induced T cell loss." (PMID 29135922, 2017). "We further investigated whether the enlarged population of CD4+ DCs in the bone marrow was associated with the loss of DCs in the spleen during the course of sepsis." (PMID 29218051, 2017). "Given the similar trend of the in vivo and in vitro studies, we hypothesize that Mfn2 might be a regulatory factor of CD4+ T cell apoptosis in sepsis and autophagy deficiency might be the molecular mechanism." (PMID 29358849, 2017). "Furthermore, a lower percentage of BTLA+/CD4+ T cells during the early stage of sepsis is associated with the severity of sepsis and the mortality of patients with sepsis." (PMID 26329820, 2015). "Furthermore, lower percentage of BTLA+/CD4+ T cells during the early stage of sepsis is associated with the severity and the mortality of septic patients." (PMID 26329820, 2015). "Unlike other co-inhibitory receptors, our results suggested that lower levels of BTLA expression on CD4+ T cells during the early stage of sepsis may increase the risk of pejorative outcome." (PMID 26329820, 2015). "Persistent inflammation, impaired CD4+ T-lymphocytes activation, and caused T-lymphocytes exhaustion may be associated with decreased survival in elderly patients and mice after sepsis." (PMID 26543853, 2015). "Suppressed cytokine production of Th1/Th2/Th17 by Atg7-deficient CD4+ T cells after sepsis may therefore be partially mediated by insufficient energy secondary to autophagy deficiency." (PMID 25029098, 2014). "Suppressed cytokine production may be mediated by defective mRNA transcription rather than defective secretion, as mRNA expression of two cytokines (IFN-γ and IL-10) were decreased in autophagy-deficient CD4+ cells after sepsis (unpublished data)." (PMID 25029098, 2014). "It will be valuable to determine whether sepsis causes a relative or absolute increase in CEACAM1 expressing CD4+ T-cells in future studies." (PMID 23894299, 2013). "The persistence of an elevated ratio of Treg cells to all CD4+ T cells during sepsis has been reported to be associated with a prolonged immunosuppression after the acute phase of sepsis, a predisposition for secondary nosocomial infections and a poor prognosis." (PMID 23209626, 2012).
Sepsis (continued). "In the case of severe sepsis, studies of both human patients and mouse models have identified numerous phenomena associated with post-septic CD4+ T cells; these include activation-induced cell death, reduced proliferative capacity and modulations in pro-inflammatory gene expression." (PMID 21655295, 2011). "Moreover, a lower CD4+ ATP content at the time of ICU admission is associated with a worse clinical outcome in those suffering from sepsis." (PMID 20540723, 2010). "Furthermore, we have demonstrated that a lower CD4+ ATP content is associated with a worse clinical outcome in those suffering from sepsis, and importantly, this finding is present at the time of ICU admission." (PMID 20540723, 2010). "In another study using the CLP model, mice with CB2R knocked out in CD4+ T cells showed improved survival and increased IL-10 production upon CB2R activation, indicating that CB2R activation in CD4+ T cells may enhance sepsis susceptibility by inhibiting IL-10 production." (PMID 38775488, 2024). "In our pivotal study, we found that an absolute number of < 400/μL CD4 T lymphocytes at hospital entry was independently and strongly associated with in-hospital mortality in a large sample of patients hospitalized at an Infectious Disease Unit with the suspect of sepsis." (PMID 34372784, 2021). "Interestingly, the tight and strong association of CD4 T lymphocytes with sepsis prognosis was quite relevant in comparison with other biochemical markers commonly used to stratify outcome of patients with sepsis." (PMID 34372784, 2021). "CD4+ lymphocyte adenosine triphosphate (ATP) might be a new marker in sepsis-associated AKI." (PMID 34616308, 2021). "In addition, a clinical research showed that CD4+ lymphocyte ATP might be a new marker in sepsis-associated AKI because of its correlation with survival in sepsis." (PMID 34616308, 2021). "Cytokine “help” from CD4 T cells is a hallmark of this population of immune cells, and the prolonged dysfunction in cytokine production may contribute the generalized immunoparalysis seen during sepsis." (PMID 32903436, 2020). "Finally, to determine whether the sepsis-induced loss of MOG-specific CD4 T cell precursors is causal in the reduced disease severity of EAE mice, the same 2D2 transfer and surgery groups were used as before and disease progression was monitored." (PMID 33191915, 2020). "Thus, understanding the molecular mechanisms that cause the decline of CD4+ T cell count in patients with Candida sepsis may provide new insights into improving outcomes." (PMID 32431684, 2020). "Thus, increased frequencies of resting memory T cells in cancer septic hosts may confer a greater proportion of the CD4+ T cell compartment that is most susceptible to dysregulation in the context of sepsis." (PMID 29338031, 2018). "One limitation of this study is that, due to federal regulations, we could only perform opportunistic collection of tissues from euthanized SM infants, and several of our study animals died from sepsis-related causes that might have influenced the overall level of CD4+ T cell activation." (PMID 24604066, 2014). "Therefore, lower ATP_CD4 levels may indicate a lower risk for immune-mediated kidney damage ultimately promoting faster recovery from sepsis-associated AKI." (PMID 25522739, 2014). "Also, patients who died of sepsis featured a proportionally higher loss of CD4+ T-cells." (PMID 25541945, 2014). "The TyG index and CD4+ T-cell count individually predict sepsis outcomes, but reflect different biological aspects." (PMID 41601726, 2026). "Area under the receiver operating characteristic curve for 28-day all-cause mortality according to TyG index, CD4+ T-cell count, and TyG-CD4 in patients with HIV + sepsis." (PMID 41601726, 2026). "Our findings demonstrate that elderly sepsis patients exhibit exacerbated ERS in CD4+ T cells, accompanied by decreased CD4+ T cell count, which likely contributes to their impaired immune response and poor clinical outcomes." (PMID 40933998, 2025).
Sepsis (continued). "Sepsis-induced thymic degeneration leads to a decrease in thymic output and an increase in CD4+ T-cell senescence, promoting the progression of sepsis-related lympho-cytopenia and immunosuppression." (PMID 40153575, 2025). "To investigate this, we co-cultured CD4+ T cells from the peripheral blood of simple bacteremia patients with sepsis patient serum or healthy control serum." (PMID 41306770, 2025). "By applying the CIBERSORT algorithm, sepsis patients showed a higher proportion of neutrophil, memory activated CD4+ T cells, naive CD4+ cells, gamma delta T cells, M0 macrophages, activated myeloid dendritic cell." (PMID 40028203, 2025). "Further examination of immune cell interactions in sepsis identified a strong synergistic relationship between central memory CD4+ T cells and immature B cells." (PMID 39981259, 2025). "HMGB1 binds to TIM-3 in sepsis and suppresses the NF-κB signaling cascade within Tim-3-expressing CD4+ T cells, inhibiting T lymphocyte proliferation and the production of proinflammatory factors." (PMID 40153575, 2025). "Overall, our findings provide compelling evidence that sepsis can induce CD4+ T lymphocyte PANoptosis." (PMID 40995563, 2025). "Further investigation is warranted to assess the functional impact of this subset of naïve CD4+ T cells in the development of sepsis and as well as post sepsis recovery." (PMID 41208955, 2025). "At the same time, the proportions of CD4+ T cells and dendritic cells were decreased in the sepsis cohort." (PMID 39993996, 2025). "Sepsis-derived CD4+ T cells exhibited impaired calcium influx and reduced mobilization peaks, suggesting CRAC dysfunction." (PMID 41306770, 2025). "Several research groups have studied IL-7 in animal models of sepsis and demonstrated its ability to prevent lymphocyte apoptosis by restoring the functionality of CD4+ and CD8+ T cells, thus improving survival." (PMID 40005375, 2025). "In sepsis patients, p-STAT5 are reduced in CD4+ T cells and lower in those who die from sepsis compared to survivors." (PMID 41158471, 2025). "Although there was no significant decline in total CD4+ non‐MAIT T cells, we found that the frequency of Vα7.2+ CD4+ CD161− T cells was reduced in sepsis patients compared with healthy donors." (PMID 40041474, 2025). "Naïve CD4+ T cells represented one of the largest proportional increases in sepsis compared to bacteraemia samples (1.6log2FC)." (PMID 41208955, 2025). "Age was also inversely correlated with the proportion of naïve CD4+ T cells in both sepsis and acute organ dysfunction." (PMID 39935482, 2025). "CD4 + T cells play a direct role in modulating the host’s response to sepsis, and sepsis-induced apoptosis can result in CD4 + T cell exhaustion." (PMID 40504881, 2025). "We show increased proportions of this CD69+ naïve CD4+ T cell population, increased effector CD4+ T cells and yet decreased T cell activation in sepsis." (PMID 41208955, 2025). "Age positively correlated with the percent of central memory CD4+ (CCR7+CD45RA-) T cells in sepsis (r2 = 0.36, p=0.001) and AOD (r2 = 0.46, p=0.01)." (PMID 39935482, 2025). "TEM confirmed the presence of typical bilayer autophagosomes containing degraded ribosomes in CD4+ T lymphocytes from the sepsis group, providing further evidence of ribophagy activation." (PMID 40995563, 2025). "The expression of CTLA-4 on CD4+ T cells of sepsis patients is significantly increased, suggesting it as a potential therapeutic target." (PMID 41209006, 2025). "Our previous studies demonstrated that nuclear fragile X mental retardation-interacting protein 1 (NUFIP1)-mediated ribophagy conferred cytoprotection against apoptosis in CD4+ T lymphocytes during sepsis, thereby preserving host immunocompetence." (PMID 40995563, 2025). "Exploration of immunomodulatory therapy: Single-cell analysis reveals high expression of DPP4 in CD4+ memory T cells, which are significantly depleted in sepsis." (PMID 40124361, 2025).